LOX (lysyl oxidase)
Diseases named in the same sentence as LOX in open-access papers (continued):
Sharing a sentence is not in itself a finding about the gene and the disease.
Hypertension (24 papers, 2012 to 2025). The presence of chronic increased pressure in the systemic arterial system. "Obesity related syndromes, such as hypertension and diabetes, are reported to be associated with an increased lysyl oxidase mediated collagen cross-linking." (PMID 22348119, 2012). "However, it is unclear why LOX seems to offer a protective role in TAAD development yet causes oxidative stress in hypertension, whereas clinical manifestations of both diseases clearly differ." (PMID 33086603, 2020). "Moreover, we had a number of suggestive genes arise from our vascular tissue data, highlighted as having specific effects on the ECM including TIMP2, PSAP, FN1, VCAN, and LOX, each of which have been previously implicated in hypertension." (PMID 30931314, 2019). "Current fibrosis research has emphasized a detailed analysis of LOX isoform expression, uncovering its overexpression in lung, liver, heart, skin fibrosis, and hypertension." (PMID 40661776, 2025). "In patients with hypertension-related heart disease, OPN is closely associated with the excessive deposition of lysyl oxidase (LOX) and insoluble collagen, which leads to left ventricular stiffness and contractile dysfunction." (PMID 40396173, 2025). "In a cohort of 34 patients diagnosed with resistant hypertension and treated with up to nine different drugs, blood concentration of LOX was analyzed to identify drugs that have an impact on plasma LOX concentration." (PMID 35885053, 2022). "We have previously observed a link between up-regulated LOX and enhanced ROS production in cardiac hypertrophy, and cardiovascular remodeling in both obesity and hypertension." (PMID 35052579, 2021). "Given the central role of LOX in collagen and elastin cross-linking, we have recently assessed the contribution of LOX to vascular stiffness and hypertension." (PMID 31615160, 2019). "An association between LOX and CYP450 metabolites and COX-2 pathway has been reported in MS and hypertension." (PMID 26491436, 2015). "The irreversible LOX inhibitor BAPN was initially used to treat disorders such as hypertension, decreased wound healing, and peripheral blood mononuclear cell chemotaxis by preventing the formation of a highly cross-linked form of vascular collagen." (PMID 25790191, 2015). "This was true for very old BN rats or for younger ones or in the presence of hypertension or after lysyl oxidase inhibition." (PMID 24790086, 2014). "Interleukin-6 (IL-6), elevated in hypertension, is known to suppress LOX expression." (PMID 35885053, 2022). "In fact, our investigations also revealed that LOX is upregulated in the vascular wall of two animal models of hypertension, the spontaneously hypertensive rat (SHR) and Ang II-infused mice, and that the increase in vascular LOX levels results from the hemodynamic effect induced by hypertension." (PMID 31615160, 2019). "Instead, activation of the sympathetic nervous system or RAAS that is caused by running and hypertension induces via Ang-II the expression of OPN and subsequently of LOX which specifically activates the Col-III promoter and increases the rigidity of the ventricle due to cross-linking." (PMID 28824452, 2017). "Taken together, these results show that Ang II increases vascular stiffness through a combination of increased wall thickness, increased strain resulting from hypertension, and changes in the intrinsic material properties of the wall mediated by LOX enzymatic activity." (PMID 25875748, 2015). "The contribution of Ang II-associated signals to EGFR transactivation that target LOX is supported by several mouse models, human carcinoma cell lines and human tumor tissue relevant to the pathomechanisms of AAA, vascular remodeling and hypertension, and to primary and metastatic lung carcinoma." (PMID 32708046, 2020). "Interestingly, LOX has also been identified as a novel vascular ROS source in hypertension." (PMID 33086603, 2020).
Hypertension (continued). "More interestingly, the upregulation of LOX in hypertension is partially responsible for the enhanced vascular stiffness and the higher production of ROS from different sources found in these hypertensive models, as revealed in experiments in which LOX activity was inhibited by BAPN." (PMID 31615160, 2019). "Lysyl oxidase could modulate virtually all stages of the atherosclerotic process, from endothelial dysfunction and plaque progression to calcification and rupture of advanced and complicated plaques, and contributes to vascular stiffness in hypertension." (PMID 31615160, 2019). "Similarly, although LOX inhibition could decrease vessel stiffness and this might have beneficial effects to protect from cardiovascular events in hypertension, chronic LOX/LOXLs blockade could promote plaque instability, while the risk of vascular aneurysm and dissection should not be ignored." (PMID 31615160, 2019). "Our aim was to investigate the differential influence of losartan metabolites on myocardial LOX and CCL in an experimental model of hypertension with myocardial fibrosis, and whether EXP3179 and EXP3174 modify LOX expression and activity in fibroblasts." (PMID 28157237, 2017). "It is important to note that arterial stiffening is not the unique determinant of hypertension, but many other mechanisms might operate, and therefore, the contribution of LOX should be specifically addressed." (PMID 31615160, 2019). "However, there is no information on the effects of this drug on myocardial LOX and CCL in hypertension." (PMID 28157237, 2017).
Obesity (24 papers, 2012 to 2026). Accumulation of substantial excess body fat. "TIMP2 promotes intramuscular fat deposition in the muscle of chickens via the ECM receptor interaction signaling pathway, while LOX accelerates collagen fibril cross-linking associated with obesity and fibrosis progression." (PMID 40723406, 2025). "Elevated PA in individuals with obesity can cause LOX dysregulation via activation of HIF-1α, resulting in abnormal collagen deposition in the ovary and anovulation." (PMID 38333108, 2024). "Increased PA in individuals with obesity can cause LOX upregulation via the activation of hypoxia-inducible factor-1α (HIF-1α), resulting in abnormal collagen deposition in the ovary and anovulation, which can be ameliorated by metformin therapy." (PMID 38333108, 2024). "We have shown that increased PA levels in individuals with obesity are a cause of LOX overexpression in the ovary, which can result in excessive collagen deposition, thus leading to impaired ovulation." (PMID 38333108, 2024). "The ability of BAPN to reduce leptin levels in vivo and prevent the leptin-mediated induction of profibrotic mediators and ROS in cardiac cells suggests that the interaction between leptin and LOX regulates downstream signaling pathways underlying the development of myocardial fibrosis in obesity." (PMID 31766500, 2019). "Therefore, the aim of this study was to explore the role of LOX activity in adipose tissue remodelling and in the metabolic disturbances associated with obesity." (PMID 26035864, 2015). "High antioxidant activity was observed for the tested seeds through various mechanisms of action, anti-diabetic, anti-obesity and anti-inflammatory activity, including the highest activity towards LOX." (PMID 38814437, 2024). "The improvements in obesity conditions induced by LOX inhibition combined with metformin were investigated in a high-fat diet-induced obese rat model." (PMID 38333108, 2024). "Metformin improved ovulatory function in individuals with obesity by attenuating LOX expression and excessive collagen deposition in the ovary." (PMID 38333108, 2024). "Does palmitic acid (PA), the most common saturated free fatty acid (FFA) in individuals with obesity, contribute to anovulation through upregulation of the collagen-crosslinking enzyme lysyl oxidase (LOX) in the ovary?" (PMID 38333108, 2024). "Further, while obesity increased collagen deposition in adipose tissue, exercise reduced collagen deposition and gene expression of LOX and other fibrotic genes to levels similar to lean mice." (PMID 37296891, 2023). "Our results demonstrate higher LOX activity in obesity, suggesting enhanced ECM cross-linking and higher adipocyte tissue stiffness." (PMID 35008946, 2022). "In patients with OSA and obesity, more severe OSA was associated with worsened fibrosis, and circulating levels of LOX (which is regulated by HIFs) are higher in patients with obesity and more severe OSA." (PMID 34692739, 2021). "More recently, LOX inhibition has been reported to reduce body weight gain and to improve the metabolic profile in diet-induced obesity in rats when orally administered with β-aminopropionitrile at 100 mg/kg bw/d." (PMID 30650583, 2019). "For example, while it has been shown that the downregulation of LOX contributes to the aortic stiffening in an obesity mouse model, other studies have shown that inhibition of LOX attenuated the angiotensin II induced aortic stiffening." (PMID 29603864, 2018). "Our research showed that BBR can decrease the mRNA expression of LOX in eWAT at the state of obesity induced by HFD." (PMID 30622603, 2018). "More interestingly, we observed that inhibition of LOX activity protects against diet-induced obesity, thereby limiting weight gain, attenuating the disturbances in adipose tissue and improving the insulin resistance observed in obese animals." (PMID 26035864, 2015).
Obesity (continued). "In view of the low expression of LOXL isoenzymes in human adipose tissue, these data suggest that the upregulation of LOX observed in obesity has multiple consequences for the physiology of adipose tissue." (PMID 26035864, 2015). "PA concentration and LOX protein abundance and activity in follicular fluid and ovarian tissue were compared between control (n = 21) subjects, patients with obesity with ovulation (n = 22), and patients with obesity with anovulation (n = 16)." (PMID 38333108, 2024). "However, under pathologic conditions such as obesity, LOX is upregulated leading to dysregulation in matrix remodeling that generates a positive pro-obesity feedback loop." (PMID 38468823, 2024). "However, more work is required to demonstrate the relationship between obesity, LOX and BC metastasis." (PMID 38468823, 2024). "This study demonstrated that PA in obesity induces LOX expression and excessive collagen deposition in the ovary, which may restrict follicle growth, impair ovulation, and lead to infertility." (PMID 38333108, 2024). "Interestingly, ASPC3 was uniquely enriched for COL1A1, COL6A1, FN1, LOX, and LUM, which are fibrosis markers recently associated with a specific subset of PDGFRA+ progenitor cells in murine model of obesity." (PMID 36313560, 2022). "In a recent study we analyzed whether inhibition of LOX activity impacts on the cardiovascular remodeling of ECM triggered by obesity." (PMID 31766500, 2019). "The use of LOX inhibitors derived from β-aminopropionitrile (β-APN) is recognised to limit metastasis, and therefore could restrict obesity-associated cancers, such as those affecting colon or liver, among others." (PMID 30650583, 2019). "The strong correlation of LOX expression with pericellular fibrosis in the adipose tissue from both humans and rats, as well as the ability of BAPN to limit pericellular fibrosis in HFD-fed animals support the notion that LOX makes a relevant contribution to the fibrotic response in obesity." (PMID 26035864, 2015). "Highlighted Article: Lysyl oxidase (LOX) could play a role in the metabolic dysfunction induced by obesity, and consequently the inhibition of LOX activity could be a valuable strategy to ameliorate obesity-related metabolic disturbances." (PMID 26035864, 2015). "In summary, this study demonstrates that LOX could play a relevant role in the metabolic dysfunction induced by obesity and suggests that the inhibition of LOX activity could be a valuable strategy to ameliorate obesity-related metabolic disturbances." (PMID 26035864, 2015). "The higher expression of lysyl oxidase likely results from inflammation and obesity in offspring." (PMID 22348119, 2012). "Thus, we postulated that metformin might correct PA-induced abnormal ovarian ECM remodelling through downregulation of LOX expression, thereby improving ovulation in individuals with obesity." (PMID 38333108, 2024). "Thus, we speculate that elevated PA levels in individuals with obesity may also enhance LOX expression and collagen deposition in the ovary through activation of the inflammatory pathway." (PMID 38333108, 2024). "The upregulation of LOX/LOXLs seems to be a feature of several fibrotic processes affecting the heart, from those associated to post-MI cardiac remodeling, cardiac hypertrophy triggered by pressure or volume overload, HFPEF associated with obesity and metabolic syndrome or AF." (PMID 31766500, 2019). "However, the potential role of LOX activity in human obesity has been poorly characterised." (PMID 26035864, 2015). "Therefore, our data provide evidence that LOX plays a pathologically relevant role in the metabolic dysfunction induced by obesity and emphasise the interest of novel pharmacological interventions that target adipose tissue fibrosis and LOX activity for the clinical management of this disease." (PMID 26035864, 2015). "Changes in LOX activity could be involved in the disturbance of adipocyte function in obesity." (PMID 26035864, 2015).
Obesity (continued). "NAH derivatives with anti-obesity activity and improved safety profiles, dual COX/LOX-modulating NAHs and β-amino-NAHs acting as DPP-4 inhibitors illustrate the versatility of this scaffold in addressing complex, multifactorial diseases." (PMID 41596477, 2026). "A reduction in ECM remodeling by higher collagen cross-linkage by LOX and enhanced cell-cell and cell-matrix interactions through THBS1, lead to developing WAT dysfunction that characterizes unhealthy obesity." (PMID 35008946, 2022). "The lysyl oxidase (LOX) family of amine oxidases, including LOX and LOX-like (LOXL) isoenzymes, controls ECM maturation, and upregulation of LOX activity is essential in fibrosis; however, its involvement in adipose tissue dysfunction in obesity is unclear." (PMID 26035864, 2015). "However, it remains to be determined whether PA may play a role in the regulation of LOX expression, thus disrupting ovarian ECM remodelling and resulting in impaired ovulation in individuals with obesity." (PMID 38333108, 2024). "However, it remains to be determined whether PA plays a role in the regulation of LOX expression, thus disrupting ovarian extracellular matrix (ECM) remodelling in the ovary and resulting in impaired ovulation in individuals with obesity." (PMID 38333108, 2024). "Interestingly, LOX expression did not significantly decrease in the adipose tissue of humans nine months after bariatric surgery, which may suggest that pathological alterations in fibrosis due to obesity may not be easily reversed following weight reduction." (PMID 37296891, 2023).
pancreatic cancer (24 papers, 2013 to 2025). "Another study showed that 18-kDa propeptide domain of LOX (LOX-PP) from LOX strongly suppresses the invasive characteristics of lung and pancreatic cancer cells by targeting Bcl2 and NF-kappaB." (PMID 40661776, 2025). "Particularly in pancreatic cancers, there is extensive lysyl oxidase (LOX)-mediated crosslinking of collagen fibers in the tumor stroma, and hypoxia also stimulates stromal cells’ collagen production." (PMID 38730681, 2024). "Cox and colleagues develop PXS-5505, a first-in-class selective pan-lysyl oxidase inhibitor and show that it reduces chemotherapy-induced desmoplasia and stiffness, thereby improving chemotherapy response and survival in pancreatic cancer models." (PMID 37640930, 2023). "Drivers of collagen crosslinking in pancreatic cancer include the enzymes lysyl oxidase (LOX) and transglutaminase-2 (TGM-2)." (PMID 34205335, 2021). "This suggests that fibrillar collagen (potentially quantifiable by elastography using endoscope-guided ultrasound in the clinic) and LOX expression have potential as prognostic markers in pancreatic cancer." (PMID 26077591, 2015). "Taken together, and given the reproducibility across multiple patient cohorts, these findings argued for a significant role for LOX expression as a determinant of poor survival in pancreatic cancer." (PMID 26077591, 2015). "This is consistent with our data as the LOX-blocking antibody was unable to suppress pancreatic cancer in mice with advanced disease." (PMID 26077591, 2015). "In MIA PaCa-2 (a pancreatic cancer cell), LOX-PP attenuated the ERK and Akt activities and decreased the levels of the NF-Kβ p65 and RelB subunits and cyclin D1, which are activated by RAS signalling." (PMID 23750284, 2013). "Additionally, LOX inhibition synergized with gemcitabine to kill tumour cells by altering stroma, which in the case of pancreatic cancer resulted in reduced fibrillar collagen and increased vasculature." (PMID 40179101, 2025). "Our data show that PXS-5505 has the potential to increase efficacy of gemcitabine against newly forming and established metastatic disease, demonstrating, in a model of established metastatic disease in pancreatic cancer, that a small-molecule pan-lysyl oxidase inhibitor can potentiate chemotherapy." (PMID 37640930, 2023). "Furthermore, in pancreatic tumors treated with both a lysyl oxidase inhibitor and immune therapy, a decrease in pro-tumorigenic TAMs and an increase in CD8+ Granzyme B+ T-cells (anti-tumorigenic) was associated with increased survival." (PMID 35205728, 2022). "A high expression of LOX was detected in metastatic pancreatic cancer in the mice model." (PMID 35433829, 2022). "Interestingly, in one study, the combination of LOX-PP with the chemotherapeutic agent doxorubicin in breast and pancreatic cancer cells in vitro showed an enhanced cytotoxic effect of doxorubicin when the cells were first sensitize by incubation with LOX-PP." (PMID 26258070, 2015). "Finally, in PANC-1 pancreatic cancer cells, LOX-PP also impaired AKT and ERK activity and growth in soft agar and cell migration." (PMID 26258070, 2015). "Additionally, LOX is considered to be a potential relapse marker for pancreatic cancer patients." (PMID 34604236, 2021). "In this regard, recent studies have reported that LOX inhibition suppresses lung metastasis and further provides a pre-clinical rationale for using LOX inhibitors to potentiate chemotherapy responses in terminal cancers such as pancreatic cancer and triple negative breast cancer." (PMID 34572752, 2021). "Moreover, LOX was 1 out of only 5 probe sets that overlapped between the Glasgow cohort and the Collisson signatures of poor prognosis in pancreatic cancer (the others being S100A2, TWIST, NT5E and PAPPA)." (PMID 26077591, 2015).
pancreatic cancer (continued). "In an effort to identify crucial biomarkers for pancreatic cancer prognosis, a study discovered a total of four genes, ACSL5, SLC44A4, LOX, and TOX3, showing correlation with PFS as indicated by qPCR and immunohistochemical staining." (PMID 39108264, 2024). "Hypoxia plays a critical role in pancreatic cancer progression by inducing HIF1 to activate numerous genes involved in invasion and metastasis, such as NF-κB, MMP-2, quiescin-sulfhydryl-oxidase-1 (QSOX1), CX3CR1, and lysyl-oxidase (LOX)." (PMID 30060755, 2018).